CXCL8 (C-X-C motif chemokine ligand 8)
Diseases named in the same sentence as CXCL8 in open-access papers (continued):
Sharing a sentence is not in itself a finding about the gene and the disease.
COVID-19 (continued). "Data analysis demonstrated an increased order of magnitude (≥3x) for CXCL8, CCL3, IL-6, IFN-γ, G-CSF and decreased order of magnitude (≤0.3x) for CCL11, IL-4, IL-5, IL-10, PDGF and IL-7 in COVID-19 patients throughout the kinetic follow-up." (PMID 36451835, 2022). "While responses were not different between bamlanivimab- treated individuals and those who received placebo, CCL2, CCL19, CCL20, CXCL8 and CXCL10 were upregulated in samples from the nasopharyngeal cavity and the circulating blood of patients with COVID-19." (PMID 35303909, 2022). "Plasma levels of IL-1RA, IL-10, IL-15, and G-CSF and of the chemokines CCL3, CCL4, CXCL8, and CXCL10 were significantly increased in patients with COVID-19 compared with those of healthy controls." (PMID 34793331, 2022). "Meanwhile, CXCL8, S100A8, S100A9, S100A12, FCGR1A, PADI4, and BCL2A1 showed significant increases in severe COVID-19 when compared with mild COVID-19 (p <0.05)." (PMID 36159873, 2022). "Molecular docking suggested that active ingredients (including: licopyranocoumarin, Glycyrol and 3-3-Oxopropanoic acid) in LHQW played a role in treating COVID-19 by acting on CSF2, CXCL8, CCR5, NLRP3, IFNG and TNF." (PMID 36506032, 2022). "Only levels of IL1B, neutrophil chemotactic CXCL8, and alarmins S100A8/S100A9 were comparably elevated in KD and COVID-19 compared to their respective controls." (PMID 36159873, 2022). "Single-cell RNA sequencing (scRNA-seq) shows classical monocytes as the primary source of cytokines and chemokines in severe COVID-19, such as CCL2, CXCL8, IL-6, TNF-α." (PMID 35401519, 2022). "In contrast, COVID-19 featured higher IL-5, IL-7, IL-17A, CXCL8, and VEGF; CXCL8 was three-fold higher in COVID than in MAS, and VEGF is absent in MAS-induced cytokine storms." (PMID 35401519, 2022). "IL6, CXCL8, EGFR, FOS, PIK3R1, and NFKB1 were identified as common targets from the common pathways between cancers and COVID-19 (signaling by interleukins, TLR signaling, TNF-α signaling via NF-kB)." (PMID 34067609, 2021). "A previous study that examined circulating cytokine levels from people with severe COVID-19 showed a decrease in IFN-γ and increased IL-6, CXCL8, IL-1β, and CCL2, as compared to healthy controls." (PMID 34108966, 2021). "Patients with MIS-C showed higher plasma levels of C reactive protein (CRP), MPO, IL-6, and of the pro-inflammatory chemokines CXCL8 and CCL2 than COVID-19 children." (PMID 33841438, 2021). "PPI network for the immunity and inflammation cytokines in COVID-19 among R. crenulata targets showed that IL-10, IL-6, IL-1B, TNF-α, CCL2 and CXCL8 were important nodes in the network." (PMID 34313585, 2021). "Cytokines such as TNF- α, CCL2, CXCL8, and IL6, which show high levels in COVID-19 patients requiring ICU admission, can predictably be inhibited by the bioactive components." (PMID 34513735, 2021). "We found 35 novel drugs that inhibit targets (ALPL, CXCL8, and IL6) already in clinical trials for COVID-19." (PMID 34582497, 2021). "In contrast, miR-3168 was significantly downregulated in COVID-19 ARDS (log2FC=-2.13, padjusted=0.003) and targeted interleukin-8 (CXCL8) in a completely activated network." (PMID 34956213, 2021). "Our data show increased cytokine and chemokine gene expression, including CXCL8, IL-1β, and CCL3 (MIP-1α) in both mild and severe COVID-19, compared to healthy controls." (PMID 34108966, 2021). "In terms of specific transcripts, the expression levels of genes relating to neutrophil chemotaxis such as CXCL1, CXCL2, CXCL6, CXCL8 and CCL2 have consistently been found to be up-regulated in COVID-19 patients." (PMID 34149717, 2021). "The overexpression of neutrophil chemoattractants such as CXCL1, CXCL2, CXCL3, CXCL5, IL-8 (CXCL8), and CCL20 in the lungs of COVID-19 patients suggest that these cells can express neutrophil chemokines after SARS-CoV-2 infection." (PMID 34737734, 2021).
COVID-19 (continued). "It was first reported that several pro-inflammatory cytokines and chemokines, including IL-2, IL-7, IL-10, CXCL10 (IP-10), CXCL8, CCL2 (MCP1), TNFα, and IFNγ were higher in the plasma of COVID-19 patients as compared to healthy controls." (PMID 33363221, 2020). "CXCL8 was highly enriched in BALF from severe cases compared to healthy donors and mild cases of COVID-19, which correlated with abundant neutrophils in lungs of patients of that group." (PMID 33613280, 2020). "Based on our results, we suggest that controlling high-severity-specific markers (FOS, CXCL8, HLA-A, JAK3, ICAM1, and H2BC4) and low-severity-specific markers (IL1B, CD3D, CD4, CCL5, and SNRPB) may prevent COVID-19 progression." (PMID 41155463, 2025). "Similarly, several studies have reported the overexpression of chemokines in COVID-19, such as C-C motif chemokine ligands 8 and 11 (CCL8 and CCL11), and C-X-C motif chemokine ligands 2, 8, 9, and 16 (CXCL2, CXCL8, CXCL9, and CXCL16)." (PMID 40722944, 2025). "For this purpose we relied on the Comparative Toxicogenomic Database (CTD), GeneMANIA, and ToppGene Suite portal and identified a set of five common genes (IL1B, CXCL8, IL6, IL10, TNF) for the six metals and COVID-19, all of which code for pro-inflammatory and anti-inflammatory cytokines." (PMID 38963144, 2024). "U tu su svrhu korišteni Komparativna toksikogenomska baza podataka (CTD), GeneMANIA i ToppGene Suite portal te je identificirana skupina od pet zajedničkih gena (IL1B, CXCL8, IL6, IL10, TNF) za šest metala i COVID-19, koji svi kodiraju proinflamatorne i antiinflamatorne citokine." (PMID 38963144, 2024). "Additionally, studies have demonstrated that in COVID-19 patients, the increase in viral load corresponds to the upregulation of critical chemokines, including CCL7, CCL2, CXCL8, and others." (PMID 38812521, 2024). "Our dataset demonstrated downregulation of both CXCL5 and CXCL8 in COVID-19 (+) lung biopsy specimens, with these genes having the most negative Log2 fold change difference compared to COVID-19 (−) lung tissues." (PMID 38932146, 2024). "Consequently, patients with severe COVID-19 have considerably higher blood levels of IL-2, IL-6, TNF-α, IL-1, IL-10, IFN-γ, IL-8/CXCL8, and CXCL10/IP-10 during the cytokine storm, potentially because of NF-κB via selective activation." (PMID 36851766, 2023). "Indeed, previous studies have defined IL-6, IL-8/CXCL8 and, IP-10/CXCL10 as early prognostic parameters of COVID-19 severe disease." (PMID 36997530, 2023). "The combination of antibody values against CXCL5, CXCL8 and CCL25 at month 6 alone could correctly assign formerly hospitalized and outpatient COVID-19 convalescents with an accuracy of 77.5% (‘COVID-19 hospitalization signature’)." (PMID 36879067, 2023). "Significant decreases in plasma concentrations of the pro-inflammatory cytokines IL-6, TNF, and IFN-γ, the leukocyte chemoattractants CXCL8, CXCL10, and CCL2, and the anti-inflammatory cytokines IL-10 and IL-1Ra were observed in COVID-19 patients during dexamethasone treatment." (PMID 37614228, 2023). "Transcriptome analysis of BALF samples indicated that the levels of pro-inflammatory chemokines such as CXCL1, CXCL2, CXCL6, CXCL8 (IL-8), CXCL10 (IP-10), CCL2 (MCP-1), CCL3 (MIP-1A), and CCL4 (MIP-1B) are elevated in patients with COVID-19, which correlated with disease severity." (PMID 36111104, 2022). "Therefore, CXCL8, CCL2, and CMV seropositivity should be considered as new prognostic factors for severe COVID-19 courses." (PMID 36232655, 2022). "CXCL8, along with IL-37 and CRP, could be combined into a highly sensitive model to effectively differentiate severe cases from moderate ones in the COVID-19 population." (PMID 35037831, 2022). "Therefore, licorice is proposed as an effective candidate for the treatment of COVID-19 through STAT3, IL2RA, MMP1, and CXCL8." (PMID 36120307, 2022).
COVID-19 (continued). "Importantly, above immune findings were used for a Bayesian network model, which significantly revealed FOS, CXCL8, IL1β, CST3, PSAP, CD45 and CD74 as COVID-19 severity predictors." (PMID 36532041, 2022). "Molecular docking showed that Glycyrol, Phaseol and Glyasperin F in licorice may playe a role in treating COVID-19 by acting on STAT3, IL2RA, MMP1, and CXCL8." (PMID 36120307, 2022). "Higher concentrations of CXCL8 and CCL2 in the plasma, with reduced mRNA expression presumably through negative feedback mechanisms, as well as CMV-positive status, correlated with more severe courses of COVID-19." (PMID 36232655, 2022). "Interestingly, treatment of monocytes with the STAT-inhibitor and COVID-19 drug Ruxolitinib not only reduced the expression of STAT-targets CXCR4 and NAMPT, but also increased the expression of proinflammatory markers CXCL8 and CXCL2." (PMID 35998224, 2022). "Currently, only a clinical trial is evaluating the effect of an anti-CXCL8 antibody for the treatment of COVID-19 (NCT04347226), but no results have been posted." (PMID 35674675, 2022). "Finally, using a Bayesian Network model, we identified FOS, CXCL8, IL1β, CST3, PSAP, CD45 and CD74 as predictors of the COVID-19 disease." (PMID 36532041, 2022). "As IL-8/CXCL8 circulating levels are elevated in COVID-19 patients with high lung function impairment (high admission RALE score) along with neutrophil counts, IL-8/CXCL8 neutralization might exert beneficial effects in pulmonary complications of the disease." (PMID 36035415, 2022). "CXCL8 expression was significantly lower on days 1, 7, and 14, and the concurrent CCL2 expression was significantly lower on days 1 and 7 in patients with more severe courses of COVID-19." (PMID 36232655, 2022). "Therefore, more research on the antagonism of CXCL8, CCL2, CCL3, and CXCL10 in influenza and COVID-19 is required." (PMID 35674675, 2022). "In the BAL fluid of patients with COVID-19, significantly increased and extremely high levels of the cytokines IL-1β, IL-1RA, IL-17A, TNF-α, and G-CSF and the chemokines CCL7, CXCL1, CXCL8, CXCL11, and CXCL12α were found in comparison with BAL fluid of patients with influenza." (PMID 34793331, 2022). "BMS-986253 is a monoclonal anti-CXCL-8 antibody and is currently being studied for its potential impact on COVID-19 Similarly, reparixin, a CXCR1 and CXCR2 receptor antagonist, is currently in clinical trials for its use in COVID-19." (PMID 34421600, 2021). "In COVID-19 patients with ARDS, hyperinflammation occurred due to the proinflammation cytokine release in high numbers and also due to the secretion of chemokine in large numbers (CCL2, CCL3, CCL5, CXCL8, CXCL9, and CXCL10, among others)." (PMID 34367545, 2021). "To investigate the role of cytokines and chemokines in the inflammatory status of COVID-19 and MIS-C, we measured plasma levels of IL-1ß, IL-2, IL-4, IL-5, IL-6, IL-10, TNF-α, IL-17A, IFN-α, IFN-γ, CXCL10/IP-10, CXCL8/IL-8, CXCL9/MIG, CCL5/RANTES, and CCL2/MCP1." (PMID 33841438, 2021). "Moreover, a significant correlation between COVID-19 severity and the serum concentrations of IL-1, IL-2, IL-6, IL-7, IL-10, TNF-α, G-CSF, CCL2, CCL3, CXCL8, and CXCL10 has been observed." (PMID 34209845, 2021). "Moreover, a much larger proportion of these neutrophils was in a hyperactivated state in COVID-19 patients, marked by upregulated IL1B, CXCL8 and S100A12 expression." (PMID 34226537, 2021). "For example, pro-inflammatory cytokines and chemokines CXCL8 (q < 2.0 × 10−16), IL18 (q = 0.009), and IL1B (q < 2.0 × 10−16) were elevated in monocytes from male patients with severe COVID-19 compared to females." (PMID 34330889, 2021). "Accordingly, higher levels of the chemokines CXCL8 (46.9 pg/ml [0.72 to 100.34] vs 15.3 pg/ml [0 to 39.8], p = 0.018) and CCL2 (590.4 pg/ml [33.8 to 1,116.8] vs 105.6 pg/ml [3.23 to 588.5]) were detected in MIS-C than in COVID-19 (p = 0.0086)." (PMID 33841438, 2021).
COVID-19 (continued). "Increased levels of CXCL2 and CXCL8 have been shown through Transcriptional analysis of peripheral blood mononuclear cells and BALF from COVID-19 patients, to contribute to the recruitment of neutrophils to the lung, which then exacerbate the inflammatory response." (PMID 34737734, 2021). "In this study, 44 potential targets were obtained through the intersection of the disease targets of COVID-19 and the action targets of AE, which are mainly related to inflammatory or immune factors, such as IL-6, MAPK1, MAPK8, IL1B, RELA, CXCL-8, CCL2, and PTGS2." (PMID 33658066, 2021). "The analysis of the plasmatic levels of inflammatory chemokines and cytokines in patients with COVID-19 and MIS-C showed higher levels of IL-6, CXCL8, CCL2/MCP-1, CXCL9/MIG, and CXCL10/IP-10 in MIS-C, whereas CCL5 levels were significantly higher in the COVID-19 group." (PMID 33841438, 2021). "Chemokines such as IL-8/CXCL8 and proinflammatory cytokines such as IL-6 (p<0.05) and TNFα (p<0.05) were increased 1.4-, 4.7-, and 1.3-fold, respectively, in the plasma of patients with critical COVID-19, in comparison with patients with mild disease." (PMID 34122423, 2021). "Consistently, in this study we found the expression of a large number of cytokines are significantly elevated in COVID-19 patients BALF samples compared to control, including pro-inflammatory cytokines CXCL1, CXCL2, CXCL6, CXCL8, CXCL10/IP-10, CCL2/MCP-1, CCL3/MIP-1A and CCL4/MIP1B." (PMID 32228226, 2020). "The results suggest that specific chemokines (such as CXCL8 and CXCL10) may play an important role in the development of COVID-19 related symptoms." (PMID 33132913, 2020). "Furthermore, in a kinetic study, the plasma CXCL8, CCL2 and CCL7 levels were higher in fatal cases compared to the mild and/or severe cases of COVID-19." (PMID 33613280, 2020). "Their results show that in BALF from COVID-19, the differentially expressed genes (DEGs) included up-regulated proinflammatory chemokines genes, such as CXCL17, CXCL8, and CXCL2, as well as the CXCR2 receptor, critical to neutrophil recruitment, and CCL2 and CCL7, needed for monocyte recruitment." (PMID 32612615, 2020). "Severe COVID-19 in controls, but not SOT recipients, was associated with a marked increase in several canonical proinflammatory serum cytokines and chemokines (e.g., IL-6, CCL23, and CXCL8)." (PMID 39794319, 2025). "The immune response in COVID-19, which may result in ARDS, involves the unbalanced secretion of various inflammatory cytokines and chemokines, including TNF-α, IL-1β, IFN-γ, IL-6, IL-10, IL–1RA, IP–10, MCP–1, and IL-8 (CXCL8)." (PMID 37600829, 2023). "Similarly, serum IL-6, CXCL8, TNFα levels were increased in hospitalized COVID-19 patients (n = 1484) compared to non-infected by SARS-CoV-2 (n = 257) and serum levels of these pro-inflammatory mediators were positively correlated with mortality." (PMID 36941580, 2023). "In COVID-19, neutrophils contribute to disease pathogenesis by producing pro-inflammatory cytokines like TNF-α and IL-6 that contribute to lung-centric and systemic cytokine storms and the chemokine CXCL8 to promote further neutrophil recruitment and augment inflammation." (PMID 38139412, 2023). "The 10- to 100-fold higher levels of the most potent human neutrophil-attracting chemokine, CXCL8, and the neutrophil-attracting chemokines CXCL1 and CXCL5 in the BAL fluid of COVID-19 versus influenza patients could explain the major neutrophil infiltration in the lungs." (PMID 34793331, 2022). "Additionally, positive correlations between admission IL-8/CXCL8, MCP-1/CCL2, IL-10, and C-reactive protein plasma levels and Δoxygen supply during hospitalization could predict COVID-19 worsening, and some studies partly corroborate these findings." (PMID 36035415, 2022). "Importantly, CXCL1 and CXCL8/IL-8 are not the only chemokines significant in the course of COVID-19." (PMID 36613652, 2022).
COVID-19 (continued). "Although this study analyzed a large number of biomarkers (71biomarkers) and suggested a correlation of some with the severity of COVID-19, we did not analyze other markers associated with the severity of COVID, such as CHI3L1 and IGFALS59, CXCL8, CXCL10, and CCL2060." (PMID 36163447, 2022). "Taken together, our findings suggest that admission values of lymphocyte counts, neutrophil-to-lymphocyte ratio and the levels of some inflammatory markers (IL8/CXCL8, MCP-1/CCL2, IL-10, and C-reactive protein) may be useful as COVID-19 outcome predictors during hospitalization." (PMID 36035415, 2022). "Therefore, we suggested that Phaseol may reduce inflammatory cell activation and inflammatory response by acting on CXCL8 and IL2RA, thereby reducing tissue damage from excessive inflammatory response and alleviating the clinical symptoms of COVID-19." (PMID 36120307, 2022). "Therefore, the active small molecules Phaseol, Glycyrol and Glyasperin F in licorice may act on CXCL8, IL2RA, STAT3, and MMP1 to treat COVID-19 by reducing tissue damage and inflammatory response." (PMID 36120307, 2022). "To explore whether the leucocyte response is limited by COVID-19, we stimulated cells with LPS or PMA/Ion, and a clear proinflammatory response with cytokines such as TNF-α, CCL3, CCL4, IL-17a, CCL23 and CXCL8 was detected in the supernatant, indicating that leucocytes are not anergic." (PMID 35901034, 2022). "The highly correlated expression of RGS2 with CXCL8, PTGS2, NAMPT, ILB1 and further inflammatory genes in COVID-19 positive nasopharyngeal swabs suggests the involvement of a common regulator, which might explain the distinct classes of COVID-19 symptoms." (PMID 36143181, 2022). "In addition, their data suggest that neutrophils could also contribute to the disease observed in COVID-19 patients, as demonstrated by CXCL2 and CXCL8 induction, differently from influenza virus infection." (PMID 35369457, 2022). "Also, serum levels of chemokines, CXCL2, CXCL8, CXCL9, and CXCL16, increased in COVID-19 patients." (PMID 34901061, 2021). "We found that severe COVID-19 patients displayed, as extensively already reported, high level of circulating inflammatory cytokines, including IL-6, TNF-α, IL-1β and chemokines such as CXCL-10, CCL-2 and CXCL-8 contributing to the diffuse inflammatory status and the so-called cytokine storm." (PMID 34473805, 2021). "As calprotectin can regulate the production of TNF-α and CXCL8 and promote NF-κB activation, elevated levels of the S100A8/S100A9 heterodimer may trigger a harmful hyperinflammatory loop in patients with severe COVID-19." (PMID 34471261, 2021). "Transcriptomic studies revealed remarkably enhanced expressions of CCL2, CXCL8, CSF3, CSF2, and CXCL10 in Calu-3 cells infected with SARS-CoV-2, inflammatory factors that were shown to be strongly elevated in the serum of patients with severe clinical symptoms of COVID-19." (PMID 34578229, 2021). "Thus, adipose IRF5 transcripts in obesity correlate positively with TNF-α, IL-1β, IL-6, CXCL8/IL-8, CXCL9/MIG, CXCL10/IP10, CCL2/MCP1, CCL5, and CCL7/MCP3, all of which can be elevated in COVID-19 “cytokine storm”; positive correlations with IL-2 and IL-12 have been reported by the same group." (PMID 33936053, 2021). "As notable difference, strong induction of neutrophil-recruiting chemokines targeting CXC chemokine receptor (CXCR) 2, such as CXCL1, CXCL3, CXCL6, and CXCL8, were found only in human basal and secretory cells with severe COVID-19 but were absent in moderately-ill Syrian hamsters." (PMID 34381043, 2021). "Moreover, there were 16 kinds of CCGFs, including HGF, CXCL8/IL-8, CCL7/cP-3, CCL2/McP-1, CXCL9/MIG, CXCL10/IP-10, IL-6, IL-18, IL-2, M-CSF, IL-1Rα, IL-2Rα/CD25, IFN-γ, CC L3/MIP-1α, FGF, and SCF which were abnormally elevated in patients who died from COVID-19." (PMID 35528178, 2022).